NLRP6 (NLR family pyrin domain containing 6)
Diseases named in the same sentence as NLRP6 in open-access papers (continued):
Sharing a sentence is not in itself a finding about the gene and the disease.
tumor (continued). "The loss of epithelial and stromal IL-18 but not NLRP6, was associated to lower tumor immune infiltrates in the lymphoid compartment and higher Programmed cell Death receptor 1 (PD-1) expression." (PMID 33255437, 2020). "Furthermore, in multivariate Cox regression, downregulation of NLRP6 and IL-18 in the epithelium was associated with a worse outcome, after adjustment on TNM tumor stage (NLRP6: OR 3.25 [95CI: 1.27–8.28], p = 0.013; IL-18: OR 2.6 [95CI: 1.02–6.63], p = 0.045)." (PMID 33255437, 2020). "NLRP6 also has a protective role in the formation of tumours." (PMID 30515917, 2019). "If NLRP6 has a more global role in suppressing inflammation, it is possible that NLRP6 may be important in dampening tumor-promoting inflammation." (PMID 24273542, 2013). "Finally, the potential tumor suppressive function of NLRP6 in HCC was analyzed." (PMID 35651286, 2023). "In conclusion, our studies demonstrate that NLRP6 potentiates PI3K/AKT pathway by promoting p85α degradation via selective autophagy and that targeting the NLRP6/p85α interaction might serve as a promising therapeutic strategy to inhibit PI3K/AKT pathway against tumour in future." (PMID 37770465, 2023). "Moreover, research has reported that re-establishing normal NLRP6 expression in tumor cells may present therapeutic advantages over preventing progress towards advanced CRC." (PMID 34571825, 2021). "The correlation between NLRP6 and tumor evolution could be explained by NLRP6-dependent regulation of some genes involved in the epithelial to mesenchymal transition, such as Wnt and Notch or the cell-intrinsic regulation of cancer cell proliferation and migration." (PMID 33255437, 2020). "Finally, finding new ways to harness the innate immunity of tumors is currently of particular interest and re-establishing normal expression of NLRP6 in tumor cells may confer therapeutic benefits by blocking progression towards advanced CRC." (PMID 33255437, 2020). "Furthermore, overexpression of NLRP6 markedly inhibited tumor growth in nude mice." (PMID 29340077, 2017). "Consistent with the findings in tumor cell lines, we also observed the upregulation of ZBP1 and NLRP6 in 4T1 tumors treated with oHSV." (PMID 38693119, 2024). "Disruption of the NLRP6/p85α interaction by the Pep9 peptide derived through the p85α secondary structure suppresses the PI3K/AKT pathway and inhibits tumour growth in vitro and in vivo." (PMID 37770465, 2023). "Our results indicated that, except for NLRP6 and GSDMC, the expressions of most PRGs were higher in tumor tissues compared to normal tissues." (PMID 37214439, 2023). "However, NLRP6 may be a possible tumor suppressor gene that may adversely regulate the E2F and MYC pathways and be linked to a higher degree of immune cell infiltration, resulting in a better prognosis in a pyroptosis risk model that can predict the prognosis of patients with HCC." (PMID 37415625, 2023). "NLRP6 and GSDME showed elevated methylation levels in tumor samples, while GSDMC showed the opposite characteristics." (PMID 35651286, 2023). "Gene expression also differed in the same tumor, with IL6 and NLRP6 being low expressed in kidney chromophobe (KICH) while GSDMC was high." (PMID 35795676, 2022). "Among these DEGs, 5 genes were down-regulated in tumor group including IL1B, AIM2, IL6, NLRP3, and NLRP6." (PMID 36127654, 2022). "We first assessed the immunofluorescence intensity of selected inflammasome components (NLRP1, NLRP3, NLRP6, AIM2, ASC, Caspase-1, IL-1β and IL-18) in tumor cells compared to normal epithelial cells, for each patient." (PMID 33255437, 2020). "Similar to NLRP6, NLRP12 was also considered to be a tumor suppressive molecule as shown in ex vivo and in vivo carcinogenic animal models." (PMID 27206676, 2016).
tumor (continued). "Here, we demonstrated that NLRP6 acts as a scaffold protein to interact with p85α and recruit RBX1 to ubiquitinate p85α for OPTN-mediated autophagic degradation, leading to PI3K/AKT activation to enhance tumour progression." (PMID 37770465, 2023). "In conclusion, our studies demonstrate that NLRP6 acts as a scaffold protein to interact with p85α and recruit RBX1 to ubiquitinate p85α for OPTN-mediated autophagic degradation, leading to PI3K/AKT activation to enhance tumour progression." (PMID 37770465, 2023). "At the end of the experiment, the tumor size and the ratio of tumor weight and body weight of the two Nlrp6–/– mice were also not significantly different." (PMID 35369462, 2022). "Although there is no described tumor immunotherapy directly involving NLRP6, this area of research represents an interesting potential." (PMID 24273542, 2013). "Administration of C. albicans promoted tumor growth in the WT model but not in the Nlrp6–/– model." (PMID 35369462, 2022). "However, our study shows that TNF-α secretion is not altered in Nlrp6−/− macrophages, indicating that PmCQ2-induced TNF-α might not be involved in the development of tumorigenesis as this cytokine is tumor promoting." (PMID 36224650, 2022).
cancer (26 papers, 2013 to 2026). A tumor composed of atypical neoplastic, often pleomorphic cells that invade other tissues. "In other types of cancer, such as skin cutaneous melanoma, the low expression of NLRP6 is associated with poor prognosis." (PMID 35650327, 2022). "Overall, the NLRP3, PJVK, TIRAP, IL18, NLRP1 and NLRP6 genes were thought to protect against cancer, while the rest of the pyroptosis genes seemed to be correlated with cancer risk." (PMID 35246158, 2022). "NLRP6 functions range from modulating immunity to bacteria and viruses, to regulating metabolic disease and inducing protection from cancer." (PMID 36911699, 2023). "Other than the colon, liver, and stomach, which have significant levels of NLRP6 expression, NLRP6 is rarely used in cancer research in other organs." (PMID 37415625, 2023). "The understanding of NLRP6 is steadily increasing thanks to ongoing investigations, but due to discrepancies in how those studies have described their link with tumors, the significance of NLRP6 in the emergence of cancer is still debatable as of this writing." (PMID 37415625, 2023). "Next, we addressed how NLRP6 orchestrates the hepatic immune environment at an early stage of cancer development." (PMID 35803930, 2022). "NLRP6 appeared to be a cancer-promoting gene in our investigation, as it contributed to shorter patient survival." (PMID 35102195, 2022). "Functional studies established that ectopic overexpression or down-regulation of NLRP6 inhibited cancer cell proliferation by inducing cell cycle arrest at the G1 phase via P21 and Cyclin D1 both in vitro and in vivo." (PMID 29340077, 2017). "The aberrant gut microbial community also increased susceptibility to colitis-associated cancer in NLRP6 inflammasome-deficient mice after AOM/DSS administration, showing the critical activity of NLRP6 for protection against inflammation-related colon tumorigenesis." (PMID 39684769, 2024). "We need further research to clarify the molecular mechanism and correlation behind NLRP6 transcription, translation, and active inflammasome production, activation, and regulation in cancer and to explore its potential application value in human malignant tumors." (PMID 37415625, 2023). "However, there is still a big undiscovered terrain in cancer that has to be investigated based on the NLRP6 inflammasome, both for the creation of new molecular medicines and for new uses of treatments that are already in clinical use." (PMID 37415625, 2023). "Indeed, NLRP6 and IL-18 are strongly involved in the regulation of the microbiome, which is now recognized as a critical player in colon inflammation favoring cancer." (PMID 33255437, 2020). "NLRP1, NLRP3, NLRC4, NLRP6, and AIM2 have been demonstrated to influence the pathogenesis of cancer by modulating innate and adaptive immune responses, cell death, and proliferation." (PMID 39684769, 2024). "It is more important for us to continue researching NLRP6, a novel form of NOD-like receptor, as the importance of NLRs in cancer becomes more apparent." (PMID 37415625, 2023). "The result revealed that the expressions of NOD2, CASP1, IL6, and NLRP6 were negatively correlated with some or most drugs, while IL6 was also positively correlated with WZ3105 and MPS‐1‐IN‐1 in the cancer therapeutics response portal database." (PMID 35574984, 2022). "CHMP4C and CASP5 were hypomethylated in most cancer types, while PLCG1 and NLRP6 were hypermethylated in most cancer types." (PMID 35795676, 2022). "The NLR family (NLRP1, NLRP3, NLRC4, NLRP6, and NLRP12) and their binding partners have mixed roles in the pathogenesis of a variety of cancers." (PMID 33584697, 2020). "NLRP1, NLRP3, NLRC4, NLRP6, NLRP7, and NLRP12 have mixed roles in the pathogenesis of a variety of cancers as reviewed here in details." (PMID 33584697, 2020). "Of these, NLRP1, NLRP3, NLRC4, NLRP6, and AIM2 influence the pathogenesis of cancer using various mechanisms of action." (PMID 33614494, 2020).
cancer (continued). "The role of NLRP6 in noninflammasome contexts has also been demonstrated in mouse models of bacterial and viral infections, cancer, and autoinflammatory diseases involving different organs and cell types." (PMID 41062723, 2025). "We observed that NLRP7 (n = 8), AIM2 (n = 10), CASP8 (n = 6), GSDMA (n = 5), GSDMB (n = 8), and GSDMC (n = 12) mainly showed hypomethylation in most cancers, and PLCG1 (n = 11), NLRP6 (n = 13), ELANE (n = 11), CASP6 (n = 5), NLRC4 (n = 12), and PYCARD (n = 8) showed hypermethylation in most cancers." (PMID 35246158, 2022).
bacterial infection (12 papers, 2013 to 2024). "In marked contrast, later findings show that NLRP6 is a negative regulator of canonical NF-κB signaling and that mice deficient in NLRP6 survive systemic bacterial infections through upregulation of NF-κB-mediated cytokines and enhanced bacterial clearance." (PMID 24886810, 2014). "In a systemic bacterial infection model, NLRP6 was found to regulate MAPK and canonical NF-kB pathway to enhance neutrophil recruitment and bacterial clearance." (PMID 38720893, 2024). "Although much less than in the intestine, NLRP6 was shown expressed in the lungs in epithelial cells and tissue-infiltrating neutrophils and macrophages after bacterial infection of humans and mice)." (PMID 38146368, 2023). "NLRP6 is frequently discussed in studies about bacterial infection and is characterized in lung studies as a negative regulator of type 2 immune response." (PMID 37415625, 2023). "Our current study found that NLRP6 deficiency can maintain the expression of tight junction protein occludin in the lung during S. pneumoniae infection, indicating that NLRP6 plays a detrimental role in the epithelial barrier against bacterial infection." (PMID 35694317, 2022). "In contrast with those bacterial infections NLRP6 was found to be a central regulator of neutrophil recruitment and function in response to K. pneumoniae infection." (PMID 35694317, 2022). "Recently, we and others have reported that the NLRP6 inflam- masome is activated during bacterial infections." (PMID 33910012, 2021). "Nonetheless, more studies are necessary to further define the differential role of NLRP6 in viral, fungal, and bacterial infections." (PMID 33910012, 2021). "According to previous studies, various NLR-containing inflammasomes have been reported to be associated with bacterial infection, such as NLRP1, NLRP3, NLRC4, and NLRP6." (PMID 29616195, 2018). "NLRP6 is a negative regulator of inflammation during bacterial infections." (PMID 24273542, 2013). "For instance, NLRP6 inhibits NF-κB and MAPK activity in mice macrophages following bacterial infection and decreases neutrophil recruitment." (PMID 37415625, 2023). "NLRP6 co‐localises with ASC, both under steady‐state conditions and following bacterial infection in vitro." (PMID 35832835, 2022). "Similar negative roles of NLRP6 were also reported during other bacterial infections such as Salmonella typhimurium, Streptococcus pneumoniae, and Listeria monocytogenes." (PMID 38720893, 2024). "Our findings are in agreement with previous studies that NLRP6 regulates host defense against bacterial infections independent of microbiota composition." (PMID 38720893, 2024). "If this is the case, targeting NLRP6 in COPD patients might be beneficial by preventing chronic inflammation and bacterial infection-driven disease exacerbation." (PMID 38146368, 2023). "NLRP6 knockout mice were found to have less bacterial burden in the lungs or BALF and show less severe lung injury in response to different bacterial infection, such as Staphylococcus aureus, Listeria monocytogenes, Salmonella typhimurium and Streptococcus pneumoniae." (PMID 36224650, 2022). "Consequently, Nlrp6−/− BMDMs and Nlrp6−/− mice produce elevated levels of TNF-α, IL-6, and KC in response to bacterial infection or TLR2 or TLR4 agonists." (PMID 25879288, 2015). "NLRP6 has no identified ligand; however, it was recently shown to play a significant role as a negative regulator of inflammatory signaling during bacterial infection." (PMID 24273542, 2013). "Additionally, Nlrp6−/− macrophages had increased NF-κB and ERK activation in response to bacterial infection." (PMID 24273542, 2013).
inflammation (8 papers, 2013 to 2026). Aberrant reaction of the microcirculation characterized by movement of fluid and leukocytes from the blood into extravascular tissues. "Gut microbiota transferred from Nlrp6-deficient to wild-type mice attenuated lung inflammation, highlighting an Nlrp6-dependent gut-to-lung axis influencing pulmonary inflammation in response to smoking." (PMID 41366206, 2025). "In addition, CS exposure altered gut microbiota composition in both wild-type and Nlrp6-deficient mice, with NLRP6 playing a critical role in controlling lung inflammation." (PMID 41366206, 2025). "Interestingly, wild-type mice cohoused with NLRP6-deficient mice show high susceptibility to DSS-induced intestinal inflammation, indicating colitogenic dysbiosis of NLRP6-deficient mice is transmissible to normal mice." (PMID 29619131, 2018). "While antibiotic treatment probably affects both gut and lung microbiota, these data suggest that the predominant gut microbiota are necessary for CS-induced lung inflammation through NLRP6 activation and subsequent lung inflammation." (PMID 38146368, 2023). "In enterovirus-induced intestinal inflammation, TRIM29 targets and degrades NLRP6/NLRP9b, thereby suppressing the host innate immune response and facilitating viral replication." (PMID 41601651, 2026).
metabolic disorders (5 papers, 2019 to 2026). "Colonic microbes trigger NLRP6-mediated secretion of IL-18, which induce the expression of antimicrobial peptides that control the colonic microbial community to regulate metabolic diseases." (PMID 31582899, 2019). "NLRP6 plays an important function in controlling the composition of the gut microbiota in metabolic diseases." (PMID 31582899, 2019). "In summary, studies should be carried out to illustrate the role and mechanism of other inflammasomes, including AIM2, NLRP1, NLRP6 and NLRC4 inflammasomes, in metabolic disorders." (PMID 40433411, 2025).
intestinal diseases (4 papers, 2019 to 2022). "Due to the high expression of NLRP6 in intestinal epithelial cells, initial studies have focused on its role in intestinal disease." (PMID 36224650, 2022). "PPAR-γ agonist can prevent colonic NLRP6 inflammasome inhibition and intestinal disorder in water-avoidance stress-stimulated C57BL/6 mice." (PMID 31255176, 2019).
gastrointestinal tumors (2 papers, 2022). "During allogeneic hematopoietic stem cell transplantation, NLRP6 protects against liver injury by inhibiting NF-κB signaling, thus reducing inflammatory cell infiltration and liver fibrosis." (PMID 35650327, 2022).
infectious disease (1 paper, 2024). A disorder directly resulting from the presence and activity of a microbial, viral, or parasitic agent in humans. "The NLRP6 inflammasome is documented to be both a positive and a negative regulator of host defense in distinct infectious diseases." (PMID 38720893, 2024).
skin disorder (1 paper, 2023). Any deviation from the normal structure or function of the skin or subcutaneous tissue that is manifested by a characteristic set of symptoms and signs. "Among all NLR members (22 up to now), NLRP3, NLRP1, NLRC4, and NLRP6 represent the most studied inflammasomes, involved in many inflammatory tissues pathologies, where NLRP3, NLRP1, and NLRC4 are mainly related to autoinflammatory skin disorders." (PMID 38068996, 2023).
NLRP6 also shares sentences with these, for which no sentence is quoted: Crohn disease (5 papers); atherosclerosis (3); colorectal (3); injury (3); type 2 diabetes (3); acute liver failure (2); breast carcinoma (2); head and neck squamous cell carcinoma (2); hemorrhage (2); Hypertension (2); periodontal disease (2); adenocarcinoma (1); bladder cancer (1); brain injury (1); cerebral infarction (1); Cognitive impairment (1); colon adenocarcinoma (1); cutaneous melanoma (1); dry eye (1); endometrial cancer (1); gout (1); hematoma (1); intestinal infection (1); leukemia (1); liver cirrhosis (1); muscular dystrophy (1); neuroblastoma (1); neurological diseases (1); non-squamous non-small cell lung cancer (1); Oral leukoplakia (1).
A further 9 diseases each share a sentence with NLRP6 in 1 paper.